CD4 (CD4 molecule)
Diseases named in the same sentence as CD4 in open-access papers (continued):
Sharing a sentence is not in itself a finding about the gene and the disease.
co-infection (continued). "HSV-2 co-infection may account for some of the variation in that relationship by boosting CD4+ T cell counts in early infection, in a manner independent of viral load." (PMID 17957262, 2007). "Similarly, the impaired specific production of IFN-γ seen in patients with VL/HIV co-infection may be related to the low CD4+ T-cell counts and the persistent activation/inflammation and exhaustion of T cells." (PMID 40145085, 2025). "Interestingly, we observed significantly lower levels of both neutrophils and MMP9 in TB/HIV co-infection compared to new pulmonary TB, likely due to the impaired production of neutrophils resulting from low CD4+ T-lymphocyte count and viability in co-infected individuals." (PMID 40574839, 2025). "Since viral load and CD4+ T-cell count vary across individuals and within them over time, we hypothesize that viral intrahost demography modulates coinfection rates and may therefore play an important but previously uncharacterized role in determining the viral recombination rate in human hosts." (PMID 38197289, 2024). "In addition, the degree of the initial CD4+T cell depletion and their associated cytokines were linked with the likelihood of LTB reactivation in a monkey with Mtb and simian immunodeficiency virus 4 (SIV-4) co-infection." (PMID 39514524, 2024). "Interestingly, we found that the levels of CD4 + T cell counts were significantly declined in HIV‐positive patients who had co‐infections, including (HIV + T. gondii, HIV + HCV + T. gondii, and HIV + HBV + HCV + T. gondii compared with HIV mono‐infection group." (PMID 36840494, 2023). "In summary, among HIV-positive adults, S. mansoni infection was associated with a range of differences in CD4 and CD8 T cell profiles, and with reduced ADCC antibody titres, suggesting that HIV specific immunity is altered, probably impaired, during S. mansoni coinfection." (PMID 37644394, 2023). "The factors associated with CD4 count decline included the presence of any symptoms, naïve treatment status, reduced adherence even to reverse transcriptase and/or protease inhibitors, IDUs status, in men gender, >45 years old, longer duration of HIV infection, and co-infection with HCV." (PMID 35368742, 2022). "Hence, co-infection with HIV may drive the CD4 internalization of HIV infected CD4+ T cells and then increase the generation of TCRαβ+ DNT cells in patients with TB." (PMID 36443691, 2022). "Although ART results in a time‐ and CD4‐dependent reduction in the risk of developing active TB by 65%, and Thailand has provided free ART for all PLWH regardless of CD4 cell count since 2014, only 82% of individuals with TB/HIV co‐infection were on ART in 2019." (PMID 35384317, 2022). "Similarly, it has been reported that HCV coinfection impacts HIV disease progression in PLWH receiving anti-retroviral therapies (ART) where HCV coinfection negatively affects the homeostasis of CD4+ T cell counts and facilitates HIV replication and viral reservoir persistence." (PMID 34456931, 2021). "In summary, these novel associations of CD4+ cells/μL with both reactivation and death as well as with the meningoencephalitis in CDR emphasize the role of these cells as risk factors for CDR and reinforce the need of a preserved immune response provided by ART in co-infection." (PMID 34591866, 2021). "On the other hand, the higher CD4+ T cells/μL count detected in HIV+ individuals infected with Enterovirus C strains compared to HIV-positive participants without enterovirus infection might indicate a cell-mediated immune response toward the co-infection." (PMID 32079128, 2020). "This allowed us to evaluate CD4 T cell lineage using both phenotypic and functional readouts; moreover, we measured co-expression of these markers to determine the variability and plasticity of the Mtb-specific CD4 T cell repertoire in the setting of human Mtb and SM co-infection." (PMID 32117277, 2020).
co-infection (continued). "Aspergillus co-infection in severe influenza patients was related with influenza subtype and excessive pulmonary inflammatory response, but had no relation with age, gender, underlying diseases, CD4+ T cells count, immunosuppressive agents, and steroids use." (PMID 33537328, 2020). "HCV co-infection may negatively influence CD4 T cell counts in HIV-infected patients." (PMID 31752729, 2019). "Therefore, in the HIV infected individual with ATLL and or HTLV-1 co-infection, the absolute CD4 cell count may mask the degree of immunosuppression." (PMID 30344845, 2018). "The absolute number of circulating CD4+ T cells remains the most clinically-relevant marker of HIV/SIV disease progression, and some studies of HIV+ human patients have shown a modest association between HPgV co-infection and higher peripheral CD4+ T cell counts." (PMID 29073258, 2017). "This co-infection model also offers a unique opportunity to identify the effector mechanisms expressed by CD4+ T cells involved in the elimination of Brucella reservoir cells and could be further used to discover new therapeutic strategies for brucellosis without antibiotic treatment." (PMID 28824630, 2017). "However, we did not identify an association between HIV coinfection and M. bovis disease, even after stratification by CD4+ counts." (PMID 27825312, 2016). "To understand the relationship between T cell activation at pleural sites of active HIV/TB co-infection with the hallmark of HIV-1 disease, i.e. CD4 lymphocytopenia, we analyzed the relationship between activation markers on CD4 and CD8 T cell in PFMC with blood CD4 T cell counts." (PMID 27870882, 2016). "Therefore, further studies are needed to determine what levels of CD8+/CD4+ T cells and their effector functions during ART and prolonged residual HIV infection still predispose HIV-1-infected individuals to developing M. tb co-infection or active TB." (PMID 26959228, 2016). "Our findings suggest that HIV-1-infected persons with CD4+ T-cell counts ≤200/μL and/or CD8+ T-cell counts ≤300/μL appear to represent high-risk populations with increased susceptibility to M. tb co-infection and/or active TB, and may require increased clinical monitoring and intervention." (PMID 26959228, 2016). "We investigated markers of immune activation (neopterin) and inflammation (CRP) in TB patients with and without HIV coinfection and their association with CD4 cell levels, and determined their predictive capacity as alternative markers of advanced immunosuppression." (PMID 26630153, 2015). "To determine the independent risk factors for co-infection with HBV or HCV in this HIV infected population, we performed an unconditional logistic regression with HBsAg positivity or HCV Ab positivity as outcomes adjusting for age, sex, CD4 count, residence, regions and number of sexual partners." (PMID 26371878, 2015). "Thus, IL-10 plays an important role in the modulation of CD4+ Th1 cells in FIL/TB co-infection." (PMID 25211342, 2014). "Our data suggest that once chronic co-infection with both viruses is established, there is very little difference as to what the order of infection was and other immune factors like CD4 T cell counts and immune activation could be the key determinant of response to therapy." (PMID 25007250, 2014). "Finally, we demonstrate that for the filarial co-infections at least, this diminished frequency of multifunctional CD4+ T cell responses was partially dependent on IL-10 as IL-10 blockade significantly increased the frequencies of CD4+ Th1 cells." (PMID 25211342, 2014). "Although, the effect of HBV and HCVinfection on HIV disease progression remains controversial, it has been suggested that, co-infection between Hepatitis C virus and HIV may be associated with a rapid decline in the CD4 count, rapid progression of HIV infection and increased morbidity and mortality." (PMID 25396023, 2014).
co-infection (continued). "In addition, factors such as greater burden of co-infections and higher rates of malnutrition may result in differences in CD4 response between children in well-resourced and resource-limited settings." (PMID 24204216, 2013). "Here we give an account of the epidemiology of HIV-1 and S. mansoni, discuss co-infection and possible biological causal relationships between the two infections, and the potential impact of praziquantel treatment on HIV-1 viral loads, CD4+ counts and CD4+/CD8+ ratio." (PMID 23849678, 2013). "However, study participants who had HIV-HBV co-infection in this study have the mean CD4 count (250 cells/mm3) which was incomparable with mean CD4 count of 141.6 cells/mm3 and 121 cells/mm3 in the studies which were conducted in South Africa and Nigeria respectively." (PMID 23721493, 2013). "Thus, in HCV/HIV co-infection, there may be a loss of recognition of HCV antigens and/or the loss of CD4+ helper function to induce CD8+ cytolytic cells which neutralize cells infected with HCV." (PMID 25977607, 2008). "Together, our findings indicate that IL-21-producing CD4+ T cells are selectively and persistently impaired in the lungs during Mtb/SIV co-infection despite antimicrobial and antiviral therapy." (PMID 42084946, 2026). "In the current study, we present a case of co-infection of pulmonary aspergillosis and cryptococcal meningitis in a late-diagnosed HIV patient with a low CD4 count." (PMID 40801018, 2025). "The baseline lipid profile, CD4+ cell count, platelets, CRP, PCT, TNF-α, VCAM-1, and HCV and HBV coinfection were evaluated." (PMID 40006998, 2025). "Studies from the early 1990s showed very high liver‐related mortality among people living with HIV and HBV co‐infection compared to people with HBV mono‐infection, especially among those with low CD4+ T‐cell counts." (PMID 40708534, 2025). "Previous studies of SIV/Mtb co-infection and HIV infection in humans and NHP have shown that SIV or HIV infection not only ablates CD4+ T cells but also reduces their intralesional motility." (PMID 41510269, 2025). "Following treatment, our study observed an increase in CD4 cell counts and a decrease in CD8 T cell count in people living with HIV/HBV coinfection." (PMID 40046188, 2025). "Co-infection promotes HIV replication, raises CD4 levels, and indicates more severe HIV clinical illnesses." (PMID 40284988, 2025). "Lower levels of CD4+ and CD8+ cells and higher level of IL4 and IL6 in patients on the day of admission were significantly correlated with the development of coinfection the following days in the hospital." (PMID 40416960, 2025). "She had a baseline CD4 count of 8/mmc and baseline serum HIV-RNA of 8279 copies/ml, along with HCV co-infection." (PMID 39971875, 2025). "Laboratory analyses included viral load, CD4 and CD8 counts, co-infection screening (hepatitis B/C, syphilis), liver and kidney function tests, haemoglobin estimation, and HIV-1/2 typing." (PMID 40684209, 2025). "Increased viral load, significant immunological suppression, and a reduction in CD4+ T cells were the most common characteristics in HBV and HCV coinfection in HIV patients." (PMID 40430507, 2025). "In our study, we revealed that patients with lower levels of CD4+ T cells and CD8+ T cells were more prone to co-infection with bacteria." (PMID 40416960, 2025). "To evaluate the role of a chronic co-infection during the MPXV challenge, we measured the abundance of Tregs (CD25+/CD127 low), both as a number of events and relative percentage of the total CD4+ cells." (PMID 40005722, 2025). "The relationship between CD4+ T cells in both peripheral blood and granulomatous tissue, and the integrity of granulomas in Human Immunodeficiency Virus (HIV)–MTB co-infection, remains unexplored." (PMID 39205309, 2024). "After co-infection with HIV and Mtb, these mice showed decrease in CD4+ T cell counts overtime and elevated HIV load in the sera, similar to the infection pattern of humans." (PMID 38799434, 2024).
co-infection (continued). "It has been shown that the number of CD4+ T cells, the main producers of cytokines, decreased in LTBI individuals with HIV co-infection." (PMID 39514524, 2024). "Immunohistochemical staining of biopsy tissues with CD3, CD4, and CD8 showed that compared to patients in the co-infection group, patients with MTB mono-infection had a denser population of T cells with positive immunohistochemical staining." (PMID 39205309, 2024). "We observed statistically significant difference in HIV viral load, baseline CD4 cell count, the route of HIV transmission, the presence of AIDS-defining diseases and HBV coinfection in patients from eastern countries in comparison to Polish patients." (PMID 37973713, 2024). "A laboratory study revealed a previously undiagnosed co-infection with HIV-1 and HIV-2, with a CD4+ T-cell count of 63/μL." (PMID 39749085, 2024). "co-infection was higher among PLWH with CD4+ T cell counts below 200 cells/μL (25.97%) and in the subgroup with CD4+ T cell counts below 50 cells/μL (46.15%)." (PMID 39597540, 2024). "Given that CD4+ T cells serve as the primary site for HIV replication, the co-infection of these cells can give rise to intricate interactions between both viruses." (PMID 38392872, 2024). "Recent evidence shows that CD4 T cell and CD8 T cell depletion occurs during co-infection of coronavirus disease and toxoplasmosis, called “polyspecific T cell exhaustion” leading to overproduction of TH2 cytokines." (PMID 38172676, 2024). "These factors included HBV and/or HCV co-infection, HIV RNA load, CD4+ T-cell count, and neutrophil (Neu) and lymphocyte (Lym) levels." (PMID 38988810, 2024). "Following P. fragile co-infection, SIV+ RMs maintained detectable VLs and decreased CD4+ T-cell counts for several weeks." (PMID 39066199, 2024). "The proportions of dendritic cell subsets, CD4+ T cells, and NK cells were lower in the HIV-1–TB coinfection group compared to the TB group, while the frequency of CD8+ T cells was higher." (PMID 38412342, 2024). "We found that the proportions of CD4+, CD3+, and CD8+ T cells were significantly different between the MTB mono-infection group and the HIV/MTB co-infection group." (PMID 39205309, 2024). "In a study conducted in Romania, a relationship was found between CD4 cell count, HIV viral load, age at first sexual intercourse, number of sexual partners, and HPV coinfection in women living with HIV." (PMID 39202638, 2024). "HIV or TB co-infection had minimal impact on the memory and activation profile of SARS-CoV-2 specific CD4+ T cells." (PMID 37841282, 2023). "HBV surface antibody production is less commonly observed with low CD4+ cell counts, high HIV viral loads, HCV co-infection, and other comorbidities." (PMID 37243000, 2023). "Among single cytokine-producing cells, a high proportion of IL-2-expressing CD4+ and CD8+ T cells were found after co-infection." (PMID 37287962, 2023). "In BALCs, the patterns of cytokine production by CD4+ and CD8β+ T cells differed between single H3N2 infection and PRRSV-2/H3N2 co-infection." (PMID 37287962, 2023). "Low proportions of CD4+ double-cytokine producers were mounted after PRRSV-2 single infection and PRRSV-2/H3N2 co-infection." (PMID 37287962, 2023). "Factors associated with HAND were older age, lower educational level, lower current CD4+ T-cell count and HCV co-infection." (PMID 35982541, 2023). "Frequencies of PRRSV-2-specific CD4+ T-cell responses were comparable between PRRSV-2 single-infection and PRRSV-2/H3N2 co-infection groups." (PMID 37287962, 2023). "In our study, we observed elevated ability of TGF-β secretion in Foxp3+CD4+ T cells in TB and HIV infection, and HIV/TB co-infection further enhanced the production of TGF-β in Foxp3+CD4+ T cells when compared with TB." (PMID 37483385, 2023).
co-infection (continued). "Compared with control group, the proportions and numbers of T lymphocytes (CD3+), helper T lymphocytes (CD4+), cytotoxic T lymphocytes (CD8+), CD4+/CD8+ and natural killer (NK) cells decreased in HIV/HBV coinfection group (P<0.05)." (PMID 38357144, 2023). "Lower CD4 + T cells, sPD-1, and immune activation were related to a rapid HBsAg decline in patients with HIV/HBV-coinfection after the initiation of cART." (PMID 37207191, 2023). "While the impact of HIV on CD4+ T cell depletion in the lymphoid tissues is well characterized, NHP studies using the Mtb/SIV co-infection model revealed protective CD4+ T cell-independent immune responses that suppressed the reactivation of LTBI." (PMID 37764928, 2023). "In a study of BCG co-infection of SIV+ rhesus macaques, animals with high plasma viraemia (>106 copies ml−1) exhibited fewer circulating CD4+ T cells and disseminated BCG52." (PMID 37814073, 2023). "It has been postulated that HSV-2 and HIV coinfection accelerate HIV disease, characterized by a persistent decline of CD4+ T cells." (PMID 37438354, 2023). "In TB and HIV/TB co-infection, TCRαβ+ DNT cells secreted more granzyme A (p = 0.002; p = 0.002) and perforin (p < 0.001; p = 0.017) than CD4+ T cells but similar to CD8+ T cells." (PMID 36443691, 2022). "In 2014, ART eligibility was further expanded to patients with a CD4 T-cell count < 500 cells/mm3, HIV neuropathy, or coinfection with hepatitis B virus." (PMID 35313941, 2022). "Most subjects, both men and women, had a nadir CD4 < 200/mm3, but the proportion of those contaminated with HIV through IVDU and with HCV coinfection was higher in women than in men, potentially explaining younger ages in women at the first primary cancer." (PMID 35053563, 2022). "Clinical evidence has shown that TB patients with HIV co-infection are likely to be misdiagnosed, as commonly occurs among untreated HIV patients with high viral load and CD4+ counts below 200 cells per mm3." (PMID 35206552, 2022). "HTLV-1, on the one hand, shares the same tropism (CD4+ T) with HIV-1, but, also on another hand, the same transmission routes lead to the frequent observation of HIV-1/HTLV-1 co-infection cases in endemic areas." (PMID 36560812, 2022). "Of the 197 patients with HIV co-infection, 163 (82.7%) were on antiretroviral therapy (ART), and 76 (38.6%) had CD4 count <100 cells/mm3." (PMID 35734322, 2022). "Half of the patients were undergoing antiretroviral treatment at the time of coinfection diagnosis, all previously diagnosed with HIV infection, with a median CD4+ count of 350 cells/μL and a viral load of 1500 copies/μL." (PMID 36287507, 2022). "This study also reported a much higher CD4+ count and HTLV-1 proviral load in HIV-1/HTLV-1 co-infections than in HIV-1/HTLV-2 co-infections." (PMID 36560812, 2022). "Regarding CD4 T-cells count, the highest mean value was detected in HIV/HTLV-2 co-infection (G3), while the lowest mean value was found in HIV/HTLV-1 co-infection (G2)." (PMID 36146762, 2022). "In the last years, breakthroughs were made in understanding the adaptive immune response, in particular, virus-specific CD4+ and CD8+ T cells, in self-limited versus persistent HBV/HDV co-infection." (PMID 35215790, 2022). "Here we present a comparative analysis of primary CD4+ T-cells and four different T-cell lines (PM-1, CEM CCR5+, MOLT4 CCR5+, and A3R5.7) to assess the influence of HSV-2 co-infection on HIV-1 replication in vitro." (PMID 36016337, 2022). "Subsequently, the generated UV-inactivated virus was used in co-infection assay in CEM CCR5+ and A3R5.7 cell lines as well as primary CD4+ T-cells." (PMID 36016337, 2022). "For patients requiring HIV and TB care, low CD4-count, HIV and TB co-infection, and extra-pulmonary TB are all indicative of poor health status requiring increased usage of healthcare services with a higher risk of incurring CHE." (PMID 36264930, 2022).